PON1 (paraoxonase 1)
Diseases named in the same sentence as PON1 in open-access papers (continued):
Sharing a sentence is not in itself a finding about the gene and the disease.
diabetes (continued). "Consistent with previous studies, ourfindings support the antioxidant and anti-inflammatory properties of PON1 acrossvarious disease states, including diabetes and cardiovascular diseases." (PMID 40834279, 2025). "The CRP is higher in non-diabetic subjects with coronary heart disease than in people with diabetes, and PON1 is the most reduced, but further investigations are needed to assess if those are the best markers." (PMID 38474211, 2024). "In type 2 diabetes mellitus (T2DM), decreased PON1 activity was found to associate with enhanced oxidative stress in patients with diabetic nephropathy, along with the development of vascular complications." (PMID 38982880, 2024). "The body’s response to insulin by GLUT4 expression is increased by PON1, but PON1 levels are independently reduced by type 2 diabetes, with a decreasing trend as diabetes progresses." (PMID 38474211, 2024). "In a model of linear regression including age, gender, diabetes, mean arterial pressure, urine protein level and creatinine clearance, PON1 was a predictor of cf-PWV." (PMID 38982880, 2024). "There is some evidence of low serum PON1 activity in patients with lipid disorders such as diabetes mellitus (DM), MI, atherosclerosis, and familial hypercholesterolemia." (PMID 36980959, 2023). "The overall evidence indicates that pomegranate treatment leads to an elevation in PON1 levels in diabetes, further supporting the potential of pomegranate as an anti-oxidative agent." (PMID 37627561, 2023). "A variety of studies have been performed to investigate the clinical relevance of PON-1 in cardiovascular disease, diabetes, cancer, or neurologic diseases; however, the received data are still insufficient and, in some cases, contradictory." (PMID 36835296, 2023). "Currently, measurement of PON1 hydrolytic activity has generally been more closely associated with ASCVD than PON1 protein concentration, because the specific activity of PON1 is variable, for example in diabetes (see earlier discussion)." (PMID 36873390, 2023). "This study was designed to assess PON1 activity levels among patients with type 2 diabetes mellitus (T2DM) in Southwest Nigeria." (PMID 37545608, 2023). "Participants who had better control had PON1 activity of 973.87 (754-1178), while the participants with uncontrolled diabetes had a PON1 value of 918.07 (576-1063) with p-value of 0.189." (PMID 37545608, 2023). "In CAD patients with diabetes mellitus, the PON-1 arylesterase activity was significantly lower compared with CAD patients without diabetes." (PMID 37175471, 2023). "Administration of recombinant PON1 to mice prior to streptozotocin-induced diabetes resulted in a decreased incidence of diabetes and higher circulating insulin levels." (PMID 38247481, 2023). "In patients with type 2 diabetes mellitus (T2DM), the severity of CAD is associated with an increase in apolA-I glycation and decrease in HDL-associated PON1 and PON3 activity." (PMID 35326240, 2022). "It has been stated that a decrease in PON-1 activity occurs in cases of high oxidative stress states, such as metabolic syndrome, obesity, uncontrolled diabetes, cardiovascular disorders, and fatty liver disease." (PMID 36356090, 2022). "PON1 protein and activity reduce the HDLs extracted from patients with diabetes by 2.8 and 1.7 times, respectively, compared to the HDLs extracted from the controls." (PMID 35453382, 2022). "The multivariate analysis likewise indicates a significant correlation between PON-1 levels and diabetes." (PMID 36463116, 2022). "Diabetes is associated with higher concentration of MPO and at the same time with lower concentration of PON-1." (PMID 36463116, 2022). "In this study, we evaluated the association between type 2 diabetes mellitus and the concentrations of MPO and PON-1 in patients with IHD." (PMID 36463116, 2022).
diabetes (continued). "The mechanism through which PON-1 protected against diabetes was promoting β-cell viability, increasing β-cell’s insulin content, and promoting insulin release from β-cell." (PMID 35055468, 2022). "They found that having the PON1-55 MM and PON1-192 Q/Q genotypes in diabetic patients instead of L/L and R/R genotypes, respectively, were related to poorer diabetes control." (PMID 35627115, 2022). "The influence of genetic variations on PON1 enzyme activity in diabetes is revealed as early as in neonates of women suffering from gestational diabetes mellitus." (PMID 33670025, 2021). "The authors suggest that the observed phenomenon seems to be a compensatory mechanism in diabetes, a disease characterized by the depletion of antioxidant potential, including PON1 enzyme activity." (PMID 33670025, 2021). "The PON1 rs662 G (192R) and the PON1 rs854560 A (L55) variants were suspected to be associated with CHD, particularly in diabetes mellitus, cigarette smoking, and older age24,49–51." (PMID 33762698, 2021). "The gavage of citral prevented oxidative stress alterations caused by diabetes, suppressed the increase in MDA (an oxidative stress marker), and attenuated the decrease of PON1 and TAC in diabetic rats serums." (PMID 34777519, 2021). "Genotypes LL and RR favorably modified the diabetes control and were connected with the higher PON1 enzyme activity." (PMID 33670025, 2021). "Due to the altered expressions of PON1 and eNOS in patients with diabetes mellitus (DM) and the association between the serum changes in these enzymes and oxidative stress indices, citral is assumed to affect the gene expressions of these enzymes in liver at the molecular level." (PMID 34777519, 2021). "On day 7 of the study, the serum level of PON1 significantly decreased in diabetic groups after the induction of diabetes compared to that of the control groups (P=0.003)." (PMID 34777519, 2021). "A possible explanation for the reduction in PON1 activity in diabetes is the displacement of PON1 by SAA, due to the inflammatory status and oxidative stress." (PMID 34063950, 2021). "Based on the antioxidant properties of PON1, there have been studies regarding the roles of PON1 in various disease entities, including cardiovascular disease, kidney failure, diabetes mellitus, neurological disorders, and sleep apnea." (PMID 34942993, 2021). "An inverse relationship between PON1 activity and inflammatory responses has been described in numerous experimental models and clinical conditions, such as cardiovascular disease, diabetes, hypercholesterolemia, and parasite infection." (PMID 32911700, 2020). "Collectively, the data suggested that the PR of PON1 was reduced in subjects with T2D, which contributed to systematic oxidative stress and inflammation in diabetes." (PMID 32235466, 2020). "The administration of PON1, prior to streptozotocin-induced diabetes, led to decreased diabetes onset rates and higher insulin levels." (PMID 31430977, 2019). "PON1 was inversely correlated with bad lipids and duration of diabetes, but it has positive correlation with good lipids." (PMID 31372141, 2019). "After statistical adjustment for diabetes, the statistical differences observed for the overweight group were lost; in the obese group, differences found for HDLc, PON1/HDLc, adiponectin, leptin, VLDL, large HDL, intermediate HDL, and small HDL persisted." (PMID 30911344, 2019). "Serum concentrations of PON1 are decreased in subjects with diabetes mellitus type 1 and feature the ability of HDL to protect LDL from oxidation." (PMID 30286142, 2018). "Many other factors that affect PON1 activity were assessed, such as age, gender, smoking, alcohol consumption, hypertension, diabetes, serum creatinine, lipid drugs, and lipid levels." (PMID 28038449, 2017). "Males, smoking, diabetes, and heart failure were identified as factors that influenced PON1 activity." (PMID 28038449, 2017).
diabetes (continued). "The present study showed that STZ-diabetic rats had diminished PON1 activity, as has previously been observed in other studies, in both humans and rodents with diabetes." (PMID 28333071, 2017). "PON1 was also shown to protect from diabetes development in mice, and PON2 was shown to affect hepatic insulin signaling and protected macrophages from high glucose-induced oxidative stress and triglyceride accumulation." (PMID 26779262, 2015). "PON1 and PON2 genotype have been linked with susceptibility to develop diabetes, glycaemic control, and diabetic microvascular complications." (PMID 26528181, 2015). "Lycopene, a carotenoid present in tomatoes, also displayed a restorative effect upon the decreased PON1 activity observed in rats subjected to experimental diabetes." (PMID 26024295, 2015). "PON1 activity is decreased in both type 1 and 2 diabetes and lower levels are associated with microvascular complications." (PMID 26528181, 2015). "Several studies have shown that PON1 paraoxonase activity decreases with aging and diabetes and is lower in smokers." (PMID 26241956, 2015). "The enhancement of PON1 activity by pomegranate was clearly demonstrated in vivo in animal models and in humans, either healthy subjects or patients with diabetes or carotid artery stenosis." (PMID 26024295, 2015). "In this regard, decreased activities of PON1 and/or other antioxidant species have been demonstrated in obesity, diabetes, and other oxidative stress-related conditions." (PMID 24799979, 2014). "Decreased PON1 activities have been reported in diseases with accelerated atherogenesis including diabetes and familial hypercholesterolemia." (PMID 25477710, 2014). "However, when the interaction term of diabetes and Q192 was added to multivariable models, the main effect of the polymorphism remained significant for the prediction of PONase but was substantially attenuated for PON1 concentration with a borderline association (β = 3.79, P = 0.08)." (PMID 25477710, 2014). "Decreased PON1 activity has been reported in various diseases such as diabetes mellitus, atherosclerotic heart disease, rheumatoid arthritis, and chronic renal failure." (PMID 24971380, 2014). "In diabetes experimental models, it has been reported that PON1 enzymatic activity is decreased and reduced PON1 activity was suggested to play a role in the severity of coronary atherosclerosis." (PMID 22738670, 2012). "Recently, studies in PON1 demonstrated that PON1 has a protective role against diabetes development, secondary to its unique antioxidant properties." (PMID 23497651, 2012). "PON1 mass was significantly associated with PON1 phenotype (P = 0.0001), HDL cholesterol (P = 0.009), LDL cholesterol (P = 0.02), and diabetes status (P < 0.05)." (PMID 22701797, 2012). "In contrast, PON1 phenotype, diabetes status, HDL cholesterol, and LDL cholesterol were all significantly associated with PON1 mass." (PMID 22701797, 2012). "The determinants of PON1 mass were determined with ethnicity and the covariates PON1 phenotype, lipoprotein concentrations, diabetes status, and renal status as covariates." (PMID 22701797, 2012). "Evidence of interactions includes the report of the association of PON1 genotype and CHD only in subjects with diabetes." (PMID 22685667, 2012). "In this regard, it should be noted that increasing PON-1 in mice attenuated diabetes-induced macrophage OS, diabetes development and decreased mortality." (PMID 19742300, 2009). "Serum PON 1 activity decreases in STZ-induced diabetic rats and in patients with vascular complications caused by type 2 diabetes mellitus." (PMID 18036220, 2007). "Many other factors, including dyslipidemias and diabetes, are involved in determining PON1 activity, and these may be more influential than any gene so far discovered that modifies PON1 activity or concentration." (PMID 40298833, 2025).
diabetes (continued). "Diabetes induction in rats increased their susceptibility to diabetes vascular complications, leading to dyslipidemia and elevating cardiovascular indices (LDL/HDL, MPO/HDL, and MPO/PON-1) (respectively)." (PMID 39877627, 2025). "Fifth, clinical variables such as the duration, severity, and treatment status of comorbidities such as hypertension and diabetes may influence PON1 levels." (PMID 40342642, 2025). "These metabolic alterationscollectively impact diabetes pathogenesis, suggesting that PON1 may influencediabetes through a more systemic mechanism." (PMID 40834279, 2025). "Consequently, further research iswarranted to explore the potential of targeting PON1 for diabetes treatment." (PMID 40834279, 2025). "Additionally, antioxidantpolyphenols obtained from some plants can increase PON1 expression by activatingPPARγ, suggesting astrong correlation between PPARγ and PON1 in diabetes." (PMID 40834279, 2025). "CAR application also improved reduced levels of PON 1 and ARES, which are associated with diabetes." (PMID 41516168, 2025). "A substantial body of research has consistently shown that PON1, which has reducedactivity in both type 1 diabetes mellitus (T1DM) and T2DM patients, plays a criticalrole in glucose metabolism and homeostasis and is functionally involved in beta-cellinsulin secretion." (PMID 40834279, 2025). "1991: Lower serum PON1 activity in familial hypercholesterolaemia and diabetes mellitus reported." (PMID 38887979, 2024). "Paraoxonase-1 (PON1), a major anti-oxidant enzyme, has been reported to contribute to the pathogenesis of asthma and many other diseases, including rheumatoid arthritis, diabetes, systemic lupus erythematosus, and psoriasis." (PMID 39684469, 2024). "The malfunction of PON1 activity has been found in both diabetes mellitus type 1 and type 2." (PMID 38474211, 2024). "The focus should also be on introducing into our diet the plant extracts that have been found to enhance PON1 levels, whose beneficial activity has been proven, and discovering novel substances that can modulate PON1, thereby delaying the onset of diabetes and cardiovascular diseases." (PMID 38474211, 2024). "Currently, measurement of PON1 hydrolytic activity has generally been more closely associated with ASCVD than PON1 protein concentration, because the specific activity of PON1 is variable, for example, in diabetes." (PMID 38887979, 2024). "PON1 activity in participants with controlled plasma glucose: participants with T2DM who had controlled diabetes based on fasting plasma glucose of less than 130mg/dL had a higher median PON1 activity compared to the participants with uncontrolled glucose levels." (PMID 37545608, 2023). "PON1 activity is diminished in dyslipidaemia, diabetes, and inflammatory disease." (PMID 36873390, 2023). "PON1 has multiple functions including the metabolism of pro-inflammatory, oxidized lipids in LDL and HDL, and has been implicated in the pathogenesis of several disorders including diabetes, coronary heart disease (CHD), cancer, and lung disease." (PMID 36138190, 2023). "The authors of the study also observed that the progression of diabetes may be accompanied by a substantial decrease in PON-1 activity." (PMID 36463116, 2022). "The level of PON1 as an antioxidant and antiatherogenic enzyme decreases in diabetes mellitus." (PMID 35453382, 2022). "In addition, the study demonstrated that the progression of diabetes correlates with a further decrease in PON-1 activity." (PMID 36463116, 2022). "In the European population the relationship between PON1 promoter polymorphisms and diabetes was not obvious." (PMID 33670025, 2021). "PON1, a major antioxidant enzyme, has been reported to contribute to the pathogenesis of asthma and many other diseases including rheumatoid arthritis, diabetes, systemic lupus erythematosus, and psoriasis." (PMID 32676117, 2020).
diabetes (continued). "Then, with the occurrence of diabetes and the related oxidation/glycation of the lipoprotein PON1 could redistribute in other subclasses." (PMID 32751395, 2020). "Dysfunctional HDLs, characterized by an increased content of MDA, MPO and ceruloplasmin, in parallel with decreased PON-1 protein and activity, were found in plasma from patients with coronary artery disease and/or diabetes and were demonstrated to play pro-inflammatory effects in EC." (PMID 33375461, 2020). "In diabetes, decreases in the activity of PON 1 have been related to glycation processes." (PMID 32566072, 2020). "It should also be noted that in addition to CVD, low PON1 activity has been reported in other disease states having a significant inflammatory component including diabetes mellitus, obesity, metabolic syndrome, cancer, and various rheumatic, renal, hepatic, and neurologic diseases." (PMID 31480611, 2019). "In addition, the administration of purified PON-1 itself was shown to reduce the development of inflammatory bowel disease and diabetes, both in animal model." (PMID 31052559, 2019). "Diabetes and positive family history in patients with overt CHD are associated with the serum PON1 activity, which might be an additional factor helpful in evaluating cardiovascular risk in this group of patients." (PMID 30935088, 2019). "Our study confirmed data showing decreased PON1 activity in patients with diabetes mellitus." (PMID 30935088, 2019). "We evaluated the relationships between paraoxonase and arylesterase activities of PON1, and classic risk factors of CHD, including sex, age, hypertension, diabetes mellitus, obesity or overweight, cigarette smoking and medical history of CHD as well as previous infarct and statin treatment." (PMID 30935088, 2019). "Glycation or non-enzymatic glycosylation of PON1 is another consequence of hyperglycemia that is associated with diabetes mellitus." (PMID 31430977, 2019). "Firstly, the glycation process of proteins (also PON1 molecule) that is characteristic for diabetes impairs their physiological functions, which may lead to decrease in PON1 activity and the serum antioxidative efficiency." (PMID 30935088, 2019). "The aim of this study is to investigate whether and how PON1 glycation contributes to endothelial dysfunction in diabetes." (PMID 28374834, 2017). "Combined, these results indicate that the HDL anti-inflammatory capacity is impaired in the context of chronic hyperglycemia, even independent of HDL cholesterol, diabetes-associated impaired PON-1 activity and enhanced low grade chronic inflammation." (PMID 29025405, 2017). "In conclusion, low PON1 activity predicted the degree of coronary lesion, particularly in multiple vessel lesions, smokers, and diabetes, which may represent a biochemical marker for the severity of CAD." (PMID 28038449, 2017). "Next, we assessed whether hyperglycemia via formation of glycated PON1 impairs endothelial function in diabetes." (PMID 28374834, 2017). "The PON1 activity level was influenced by gender, smoking, diabetes, and HDL-C levels." (PMID 28038449, 2017). "Previous studies have reported that PON1 is glycated in diabetes." (PMID 28374834, 2017). "This may be related with oxidative stress because there are numerous researches which demonstrate the role of PON-1 on the age- and oxidative stress-related diseases such as diabetes and heart diseases." (PMID 25785999, 2015). "Some authors suggested that administration of antioxidants could protect PON1 from inactivation and/or diminishment arising from ROS and consequently ameliorate diabetes and related complications." (PMID 25431786, 2014). "It has previously been suggested that decreased PON1 activity in diabetes may be due to glycation-induced changes to HDL and/or PON1, thereby affecting its association with HDL that has been related to its antiatherogenic properties." (PMID 24799979, 2014).